LCN2 (lipocalin 2)
Diseases named in the same sentence as LCN2 in open-access papers (continued):
Sharing a sentence is not in itself a finding about the gene and the disease.
psoriasis (continued). "Among the important mediators in psoriasis, LCN2 acts as an antimicrobial protein as well as adipokine associated with obesity, insulin resistance, and atherosclerotic disease, and is also responsible for the activation of the immune system in response to inflammatory and toxic stimuli." (PMID 31649677, 2019). "Based on our results, we can assume that the decrease of serum LCN2 levels represents the improvement of itch by biologics and serum LCN2 level may be a useful clinical marker for the evaluation of itch in psoriasis patients." (PMID 30805373, 2019). "To date, however, the relationship between LCN2 and itch in patients with psoriasis remains unclear." (PMID 30805373, 2019). "This in turn leads to increased expressions of multiple pro-inflammatory cytokines and chemokines, most notably LCN2, which results in increased accumulation of immunocytes, including neutrophils, and amplification and sustenance of the inflammatory cascade in psoriasis." (PMID 31024570, 2019). "To address the potential role of LCN2 in this process, we neutralized LCN2 using antibody in two mouse models of psoriasis, the IMQ model and the transgenic K14-VEGF model, and after 7 or 14 consecutive days, marked reduction in acanthosis and the number of Ly-6G labeled neutrophils was observed." (PMID 31024570, 2019). "Therefore, the aim of this study was to investigate the correlations among serum LCN2 levels and the degrees of itch and skin inflammation in patients with psoriasis and AD." (PMID 30805373, 2019). "In conclusion, serum levels of TNF-α, IFN-γ, IL-2, IL-6, IL-8, IL-18, IL-22, chemerin, lipocalin-2, resistin, sE-selectin, fibrinogen and C3 were significantly elevated and serum level of adiponectin was significantly decreased in psoriasis patients compared to healthy individuals." (PMID 29416693, 2018). "As suggested recently in a psoriasis model, LCN2 may play a role in enhancing other AMPs in the skin in concert with other cytokines/chemokines." (PMID 27442430, 2016). "Our study also supports the notion that non-lesional skin of psoriasis patients is diseased skin, as some important psoriasis genes, such as IL-22, IL-19 and LCN2, were differentially expressed between thick and thin plaque psoriasis only within non-lesional skin." (PMID 26176783, 2015). "In conclusion, LCN2 and sTNFR-1 likely play meaningful roles in the etiopathogenesis of psoriasis." (PMID 24803721, 2014). "There are a limited number of previous studies of LCN2 in psoriasis." (PMID 24803721, 2014). "We speculated that LCN2 promotes the expression of psoriasis-related inflammatory factors within keratinocytes through the 24P3R receptor, while facilitating keratinocyte proliferation and differentiation through the Fn14 receptor, but future research is needed to validate it." (PMID 40369189, 2025). "Therefore, we hypothesized that BZLF alleviated inflammation in psoriasis-like skin lesions and inhibited the proliferation of KCs, which was related to the downregulation of the LCN2/MMP-9 axis." (PMID 36950008, 2023). "Moreover, Lcn2 may potentiate the psoriasis development by enhancing Th17- and antimicrobial peptide-mediated inflammation, and Lcn2 expression is increased in the periphery and brain in other age-related CNS diseases and their risk factors." (PMID 36983014, 2023). "LCN2 may therefore be a potential target for the treatment of psoriasis." (PMID 30805373, 2019). "However, some studies have shown that LCN2 may be involved in the pathogenesis of psoriasis/PsA by modulating neutrophil function." (PMID 31467617, 2019). "They concluded by saying that lipocalin-2 may be a good predictor of psoriasis and cardiovascular risk, but not a reliable indicator of inflammation, severity of psoriasis, or antipsoriatic treatment outcome." (PMID 31275060, 2019). "The pathogenetic mechanisms of LCN2 in psoriasis/PsA are unknown." (PMID 31467617, 2019).
psoriasis (continued). "It suggests that LCN2 might play an important role in potential psoriasis/PsA pathogenesis." (PMID 31467617, 2019). "In addition, LCN2 may be involved in the tendency of patients with psoriasis to develop metabolic syndrome." (PMID 30805373, 2019). "In all five mouse phenotypes, there was increased expression of S100a9, Lcn2, S100a8, Sprr1b, Mpzl2, Has3, as well as decreased expression of Tppp, Stxbp6, and Cldn23, and each of these effects is consistent with characteristic expression patterns in clinical psoriasis." (PMID 21483750, 2011). "Overall, these results demonstrate that LCN2 and TWEAK collaboratively promote Fn14 expression in keratinocytes, which together promotes the pathogenesis of psoriasis." (PMID 40369189, 2025). "In summary, our study identifies LCN2 as a key regulator in the TWEAK/Fn14 signaling pathway, impacting psoriasis lesion development, inflammatory cell infiltration, and release of inflammatory factors." (PMID 40369189, 2025). "When combined with our research findings, this provides suggestive evidence that LCN2, TWEAK, and Fn14 interact synergistically and are highly relevant to the pathogenesis of psoriasis." (PMID 40369189, 2025). "LCN2 and TWEAK synergistically interact with Fn14, leading to epidermal proliferation and inflammation in psoriasis through the MAPK signaling pathway; however, these effects can be reversed by LCN2 knockout." (PMID 40369189, 2025). "qPCR results revealed significantly increased expression of Lcn2, Tnfsf12, Il1b, Krt5, and Krt10 mRNA in the skin of Fn14–/– mice with IMQ-induced psoriasis." (PMID 40369189, 2025). "In this study, we initially discovered the increased expression of LCN2, TWEAK, and Fn14 in the lesions from patients with psoriasis, suggesting a potential correlation among the three." (PMID 40369189, 2025). "Lipocalin 2 (LCN2) and the TWEAK/Fn14 signaling pathways are pivotal in psoriasis, influencing epidermal development, inflammatory cell chemotaxis, and inflammatory factor release." (PMID 40369189, 2025). "Lcn2 knockout reduced Fn14 expression in skin lesions and serum TWEAK levels of imiquimod-induced murine psoriasis model, while Fn14 knockout attenuated the epidermal hyperplasia-promoting effects of TWEAK and LCN2." (PMID 40369189, 2025). "By inhibiting the activation of the LCN2-dependent JAK/STAT pathway, miR-383 reduced keratinocyte proliferation and induced psoriasis apoptosis in a psoriasis animal study." (PMID 39480805, 2024). "The release of LCN2 and MPO during neutrophil degranulation exacerbate skin inflammation in psoriasis by participating in the activation of neutrophils." (PMID 39737188, 2024). "It induces the expression of other psoriasis signature genes, such as IL36G, S100A15, DEFB4A, S100A9, CXCL8, TNIP3 (coding TNF-α-induced-protein 3 or TNFAIP3), and LCN2 (by synergy of IL-17C with TNF-α) in keratinocytes." (PMID 36928592, 2023). "Thus, serum LCN2 level may be a useful clinical marker for itch in patients with psoriasis." (PMID 30805373, 2019). "Importantly, serum LCN2 levels are elevated in psoriatic patients and correlate with the severity of itching and thus might be used as a clinical marker for itching in psoriasis." (PMID 31649677, 2019). "These cytokines and LCN2 were significantly increased in DKO*K15 mice in comparison with control mice, suggesting a mild systemic inflammatory process in the HF‐SC DKO*K15 psoriasis‐like mouse model." (PMID 31556482, 2019). "The expression of specific pro‐inflammatory cytokines/alarmins, such as IL‐17A, IL‐6, and lipocalin‐2 (LCN2), was higher in the serum of DKO* mice compared to DKO*K15 mice at day 30 after psoriasis‐like induction." (PMID 31556482, 2019). "Results from qRT-PCR measurements of psoriasis-relevant transcripts showed that levels of DEFB4B, IL36G, LCN2, S100A7, S100A8 mRNA were significantly decreased in rhodomyrtone-treated cultures when compared with cytokine-treated cultures (p<0.0001, all)." (PMID 30321197, 2018).
psoriasis (continued). "Recapitulating psoriasis skin, IL-17A+TNF-α treatment lead to increased expression of DEFB4, PI3, LCN2, S100A7, and IL36G mRNA over a 72 h time course without marked deterioration of tissue structure." (PMID 30321197, 2018). "For chronic pruritus, LCN2 modulates the excitability of pruritus-related neurons via pathways such as the IL-6/STAT3 axis, and participates in the pathological processes of pruritus in allergic contact dermatitis, xerosis, atopic dermatitis, and psoriasis." (PMID 42088581, 2026). "By IHC, we found that LCN2, TWEAK and Fn14 expression was significantly elevated in skin lesions of IMQ mice, while TWEAK and Fn14 were positively correlated with LCN2 expression levels, consistent with psoriasis patients." (PMID 40369189, 2025). "However, the cell culture supernatant showed a significant increase in TWEAK expression via ELISA, indicating that LCN2 can promote M1 differentiation and the extracellular secretion of TWEAK, thereby exacerbating inflammation in psoriasis." (PMID 40369189, 2025). "Consequently, keratinocytes, neutrophils, and macrophages interact collaboratively via the LCN2-TWEAK-Fn14 signaling pathway, forming a complex network that collectively promotes the occurrence and progression of psoriasis." (PMID 40369189, 2025). "Consequently, a proposed synergistic biologic therapy targeting LCN2 and TWEAK emerges as a novel, effective approach for psoriasis treatment." (PMID 40369189, 2025). "Recently, it has been revealed that plasma levels of LCN-2 were significantly higher in psoriatic patients with nonmelanoma skin cancer than in patients with skin tumours without psoriasis." (PMID 39057409, 2024). "In a study of 62 patients with psoriasis, the BSA and PASI scores in cases of psoriatic erythroderma and psoriasis vulgaris, as well as the severity score of generalized pustular psoriasis, were all noted to have positive correlation with lipocalin-2 levels." (PMID 37546687, 2023). "LCN2 is one of the top 10 core targets in the PPI network and likely mediates biological processes involved in the external application of BZLF for treating psoriasis." (PMID 36950008, 2023). "In summary, these data suggest that LCN2, secreted by activated keratinocytes and neutrophils, is a critical inflammatory factor down-stream of TLR4/IL-36R that participates in and sustains NETs-exacerbated psoriasis inflammation." (PMID 31024570, 2019). "In the clinical setting, tissue LCN2 was found to be also significantly higher in psoriasis, regardless of dyslipidemia, or metabolic disturbance in patients." (PMID 31649677, 2019). "Although the precise mechanism by which LCN2 induces itch in psoriasis has not been determined, the results of our study suggest that LCN2 enhances itch centrally in psoriasis by a mechanism similar to that in the mouse model of AD." (PMID 30805373, 2019). "In contrast to psoriasis, LCN2 expression was not increased in AD skin, suggesting that the local effect of LCN2 on itch is limited in AD." (PMID 30805373, 2019). "Some studies have shown that serum LCN2 is not related to BMI and disease activity in psoriasis/PsA patients." (PMID 31467617, 2019). "LCN2 is induced in the epidermis by skin injury and is increased in lesional skin of patients with psoriasis, pityriasis rubra pilaris and chronic eczema, but not in those with acute eczema or atopic dermatitis." (PMID 27442430, 2016). "The list of the DEG in common in the 4 studies contains many genes known to be upregulated in psoriasis, such as IFNγ-regulated genes STAT-1, STAT-3 and MX1; antimicrobial peptides (beta defensin 4, lipocalin 2, S100A7); and pro-inflammatory proteins such as IL-8, CXCL1, IL-1F9, TNFSF10/TRAIL." (PMID 20422035, 2010). "LCN2 promotes TWEAK in keratinocytes while TWEAK upregulated the LCN2 in neutrophils, we therefore checked whether both LCN2 and TWEAK can act synergistically on Fn14 to participate in the pathogenesis of psoriasis." (PMID 40369189, 2025).
psoriasis (continued). "In patients with psoriasis, neutrophils are pre-activated and form a NET in psoriatic skin lesions NET promote keratinocyte to secrete high levels of proinflammatory factors (LCN2, IL-36γ, CXCL8, and CXCL1) by activating TLR4/IL-36R crossers and the downstream MyD88/NF-κB signaling pathway." (PMID 39737188, 2024). "LCN-2 plays many roles in the pathogenesis of psoriasis both in the differentiation and proliferation of keratinocytes and in the recruitment of inflammatory cells such as lymphocytes and neutrophils via the IL-23/IL-17 axis; thus, LCN-2 might be considered a marker of psoriasis." (PMID 39057409, 2024). "Although LCN2 injection aggravated the psoriasis-like inflammation induced by IMQ, it did not induce a psoriasis-like phenotype by itself, indicating that LCN2 may need to cooperate with certain stimuli, such as co-enhancing psoriasis with Th17 cytokines inflammatory response." (PMID 33613635, 2021). "However, the relationship between LCN2 and itch in patients with psoriasis has not been determined." (PMID 30805373, 2019). "LCN2 may not completely reflect the degree of skin inflammation of all patients with psoriasis." (PMID 24803721, 2014). "However, Lcn2 is also increased in lesional compared to non-lesional skin samples from psoriasis patients, as well as increased in the skin of a murine model of PPARδ hyperactivation with a psoriasis-like condition." (PMID 21573029, 2011). "There was not a statistical significance but a tendency that serum LCN2 levels and VAS scores were lower in psoriasis patients without itch after biologic treatment." (PMID 30805373, 2019).
diabetic nephropathy (74 papers, 2013 to 2026). "Diabetic nephropathy is often associated with tubulopathy, characterized by lesions and hyperplasia of the PTECs, and with cellular death triggered by a decrease in lipocalin-2 expression." (PMID 37675364, 2023). "In diabetic nephropathy, LCN2 depletion aggravates disease progression by increasing oxidative stress and inflammation through activating small mothers against decapentaplegic (Smad2/3) signaling." (PMID 39512683, 2024). "As atherosclerosis and diabetic kidney diseases was reported to have correlation with elevated level of LCN2, lipid profile and creatinine were also investigated." (PMID 28709459, 2017). "LCN2 was found as a biomarker of diabetic kidney diseases in urine as reported in studies done in Ohio and Brazil." (PMID 28709459, 2017).
pancreatic cancer (74 papers, 2008 to 2025). "A more recent study also observed that loss of LCN2 prevents the muscle atrophy in mice with pancreas cancer." (PMID 38035773, 2024). "LCN2 levels correlate with fat and lean mass wasting and are associated with increased mortality in patients with pancreatic cancer." (PMID 38397997, 2024). "Lipocalin-2, a protein abundant in neutrophils, has recently been implicated in appetite suppression in preclinical models of pancreatic cancer cachexia." (PMID 37006254, 2023). "It has also been noted that pancreatic cancer cachexia is associated with increased circulating levels of LCN-2, an anorexic molecule that contributes to muscle and fat wasting." (PMID 36718277, 2023). "Consistent with this, was recently demonstrated that Lcn2 downregulation, limited AT loss and inflammatory cell infiltration in a pancreatic cancer cachexia mouse model." (PMID 37517520, 2023). "In summary, the data presented here illustrate that pancreatic cancer-associated LCN2 mediates appetite suppression through its actions in the CNS." (PMID 33824339, 2021). "We next showed that genetic deletion of Lcn2 significantly increased food consumption and modestly spared both lean and fat mass loss during pancreatic cancer cachexia." (PMID 33824339, 2021). "Taken together, key observations we make in our rodent models, including neutrophil expansion, increased circulating LCN2, and lean mass loss, also occur in patients with pancreatic cancer." (PMID 33824339, 2021). "We demonstrate that LCN2 is robustly upregulated in murine models of pancreatic cancer, its expression is associated with reduced food consumption, and Lcn2 deletion is protective from cachexia-anorexia." (PMID 33824339, 2021). "Taken together, our data demonstrate that elevated LCN2 levels during human pancreatic cancer are associated with neutrophil expansion, increased fat and skeletal muscle catabolism, and decreased survival." (PMID 33824339, 2021). "Analogous to our murine models, we present human data showing associations between rising LCN2 levels and neutrophil expansion, fat and lean mass wasting, and mortality during pancreatic cancer." (PMID 33824339, 2021). "Lipocalin2 (LCN2, also known as neutrophil gelatinase-associated lipocalin), is dysregulated in a variety of cancers such as pancreatic cancer, prostate cancer, and hepatocellular carcinoma." (PMID 27912767, 2016). "LCN2 is also reported to be an early diagnostic marker for pancreatic cancer." (PMID 40109857, 2025). "Finally, we observe that LCN2 levels correlate with fat and lean mass wasting and is associated with increased mortality in patients with pancreatic cancer." (PMID 33824339, 2021). "Here, using pancreatic cancer as a model of cachexia, the authors demonstrate that LCN2 is a critical mediator of cancer-associated anorexia and may be therapeutically targeted to improve patient outcomes." (PMID 33824339, 2021). "However, a limitation of this study is that it is unclear if LCN2 regulates appetite during other chronic diseases associated with cachexia, or if there are permissive factors in the appetite-regulating effects of LCN2 that are specific to pancreatic cancer." (PMID 33824339, 2021). "Since we observed an increase in circulating neutrophils, as well as their transcriptional upregulation of Lcn2 in our rodent models of pancreatic cancer cachexia, we hypothesized that neutrophil expansion would be associated with an increase in circulating LCN2 levels during human disease." (PMID 33824339, 2021). "In terms of the tumor-suppressive role of LCN2 in pancreatic cancer, ovarian carcinoma, and hepatocellular carcinoma, LCN2 levels are extremely high during tumorigenesis and then decrease during tumor progression." (PMID 40109857, 2025). "Public database analysis confirmed a significant increase in LCN2 mRNA levels in pancreatic cancer cells treated with IL-1β for 24 h compared with those in untreated controls." (PMID 41436606, 2025).